OCLN (occludin)
Diseases named in the same sentence as OCLN in open-access papers (continued):
Sharing a sentence is not in itself a finding about the gene and the disease.
Sepsis (continued). "In addition, human brain tissues of patients with decreased sepsis showed that the TJ proteins occludin, claudin-5, VE-cadherin and zonula occludens-1 (ZO-1) in microvascular endothelial cells were downregulated, illustrating BBB dysfunction." (PMID 37474902, 2023). "Destroy of TJ proteins, such as intact membrane proteins occludin, zonula occludens (ZO-1) and claudins would lead to the disruption of intestinal barrier and hence bacteria spreading and systemic infection and inflammation, the hallmarks of sepsis." (PMID 37081964, 2023). "Although no previous studies have evaluated the effect of propofol on ZO-1 gene expression in alveolar epithelial cells during sepsis, it has been shown that propofol has the ability to increase the levels of tight junctions proteins, such as occludin, in the blood–brain barrier after hypoxia." (PMID 37575989, 2023). "Moreover, we detected substantially decreased expression of tight junction proteins in Card9−/−-sepsis mice compared with WT-sepsis mice, including ZO-1, occludin and Claudin-2." (PMID 35618701, 2022). "We confirmed experimentally that lentinan could significantly reduce the protein expression of NF-κB as well as TLR4, NF-κB, and Bax, but increase the expression of occludin and Bcl-2 in intestinal tissue of mice with gut-origin sepsis." (PMID 34790828, 2021). "Our findings suggest that analyzing of blood occludin concentration might serve as a biomarker in human sepsis for the detection of BBB damage, as already shown in a rat study with cerebral arterial occlusion." (PMID 32600371, 2020). "Although our model for sepsis was different as we used IP injections of LPS to induce sepsis, our results are similar to other studies cited above as there was a notable decrease in claudin-1 and occludin expression in BF mice." (PMID 31790417, 2019). "In addition, GIK increased the expression of tight junction proteins, including ZO-1, occludin, and claudin-1, during sepsis and thus decreased the intestinal permeability." (PMID 28428961, 2017). "During sepsis-induced damage to the blood-gas barrier, there is obvious attenuation and translocation of the tight junction proteins (including ZO-1, Claudin 5 and Occludin) in the alveolar epithelial cell membrane, demonstrating that the tight junctions are disrupted." (PMID 36093187, 2022). "In this study, the expression of the TJ proteins ZO-1, occludin and claudin-1 in the intestinal mucosa was decreased in septic rats, and the pathological morphology of the intestinal mucosa was destroyed, suggesting that sepsis leads to the destruction of the morphology of intestinal mucosa." (PMID 35576220, 2022). "Similarly, the expression of ZO-1, Occludin, Claudin-2, detected by immunohistochemistry, was increased in the intestinal tissue in Card9−/−-sepsis mice treated with Ad-Ripk2 compared with Card9−/−-sepsis mice." (PMID 35618701, 2022). "We established a sepsis model using lipopolysaccharide (LPS) stimulation, followed by an assessment of cognitive function using Morris water maze, and then Western Blot was used to analyze the expression of tight junction proteins ZO-1 and Occludin in the hippocampus of mice." (PMID 35126784, 2022). "Sepsis led to an increase in the expression of IL-6, TNF-α, and a decrease in the expression of occludin." (PMID 40822580, 2025). "The S100A8/A9, occludin, and VE-cadherin protein expression levels in the lungs of CLP-induced mice with sepsis were measured to explore the functional role of S100A8/A9 in pulmonary vascular hyperpermeability in sepsis." (PMID 37978525, 2023). "Compared with the sepsis group, the sepsis + DMOG group exhibited significantly higher expression levels of HIF-1α and ZO-1, occludin and Claudin-1 in the intestinal mucosa (P < 0.05) (P < 0.05)." (PMID 35576220, 2022).
Sepsis (continued). "However, the noteworthy feature is the significant increase in the cecal expression of “sealing proteins,” claudin-1 and occludin, in HF diet mice as compared to BF diet mice, as this suggests that both proteins may potentially play a role in improving barrier function in sepsis." (PMID 31790417, 2019). "The present results have shown that the expression of tight junctional proteins such as occludin, claudin-5, and ZO-1 was decreased in the lung tissues of CLP-induced sepsis rats when compared with the sham group." (PMID 30150933, 2018). "IPA treatment significantly promoted the expression of tight junction markers Occludin and ZO-1 in intestinal tissue of sepsis mice, which suggested that IPA treatment maintained intestinal barrier homeostasis during sepsis." (PMID 37208586, 2023). "Furthermore, the expression level of HIF-1α was lower in the sepsis + BAY 87–2243 group (P < 0.05), and the protein expression levels of ZO-1, occludin and claudin-1 protein were significantly decreased (P < 0.05)." (PMID 35576220, 2022). "We used the CLP manoeuvre to establish a murine model for sepsis-induced ALI and found that FA improved alveolar epithelial cell barrier function, as evidenced by the recovered expression of the tight junction proteins ZO-1, occludin and claudin-1." (PMID 36433644, 2022). "The expression of claudin-18 and occludin did not change during sepsis (data not shown) in left ventricular tissue." (PMID 32410859, 2020). "Staining of occludin showed a lack of focus staining within the surfaces of epithelial cells and some villi of the sepsis-injured mice, whereas MitoQ markedly alleviated these effects." (PMID 32351320, 2020). "In cultured alveolar epithelial cells isolated from rats, claudin-18 and occludin were significantly reduced during sepsis, whereas ZO-1 was not significantly affected." (PMID 32410859, 2020). "Compared with the sepsis group, the expression of NF-κB and HIF-1α mRNA and protein in ileal tissues were found to be significantly increased, while IκB, ZO-1 and Occludin mRNA and protein were significantly decreased in the miR-31 mimic group and the siRNA-HMOX1 group (all p < 0.05)." (PMID 30340459, 2018). "Furthermore, the current study showed that the rats with sepsis exhibited higher expressions of miR-31, HMOX1, NF-κB, and HIF-1α in addition to decreased expressions of IκB, ZO-1, and Occludin." (PMID 30340459, 2018). "CORM-2, but not iCORM-2, significantly reduced sepsis-induced damage of intestinal mucosa (including TJ disruption), TJ protein reduction (including zonula occludens-l (ZO-1), claudin-1 and occludin), MLC phosphorylation and proinflammatory cytokine release." (PMID 26720630, 2015). "The administration of LGG as a pretreatment for 4 weeks, prior to the induction of sepsis by cecal puncture in mice, demonstrated a greater expression of junction proteins (such as occludin), which was similar to that observed in the control group without sepsis." (PMID 39593945, 2024). "Also, in the model of sepsis-induced intestinal barrier disruption, P2X7R antagonist not only increased TEER but also showed a significant increase in expression of tight junction proteins, occludin, claudine-1, and ZO-1." (PMID 35492615, 2022). "Also, in a model of sepsis-induced intestinal barrier disruption, the P2X7 receptor antagonist showed a significant increase in the expressions of the tight junction proteins, occludin, claudine-1, and ZO-1." (PMID 34456718, 2021). "Occludin has been shown to directly interact with claudins, ZO-1, and actin at its C-terminus, and we speculate that with sepsis, the reduction in occludin expression, even without stretch, leads to a more disorganized and leaky tight junction." (PMID 22723883, 2012).
Sepsis (continued). "On the other hand, CLP treatment downregulated the expression of occludin and E-cadherin mRNA in PD-L1 KO mice and protein expression, indicating that low occludin and E-cadherin expression is part of the endogenous sepsis response, even in the absence of PD-L1." (PMID 40658180, 2025). "Therefore, in this study, we investigated the roles of sesamin in regulating the development of sepsis via the HMGB1/TLR4/IL-33 signalling pathway by examining its impacts on the production of pro-inflammatory cytokines and the expression of IL-33, HMGB1, TLR4, ZO-1, and occludin." (PMID 32893702, 2020). "This suggests that the alcohol/sepsis combination increases permeability through a different mechanism than sepsis alone, in light of the fact that we have previously shown that CLP does not upregulate either occludin or ZO-1." (PMID 23717394, 2013).
diabetes (48 papers, 2007 to 2025). "Our previous study has demonstrated a pivotal role for Occludin in the amelioration of vascular injuries associated with diabetes, specifically those mediated by APN." (PMID 39354565, 2024). "The effect is associated with downregulation of retinal VEGF mRNA and ICAM-1 expression and a reduction in the loss of retinal occludin induced by diabetes." (PMID 21139695, 2010). "rAAV-angiostatin reduced retinal occludin loss at 10 days after STZ-induced diabetes (n=5, p=0.041)." (PMID 17293777, 2007). "Treatment of diabetic rats with TNFSF15 prevented the decrease in claudin-5, occludin, and ZO-1 protein levels caused by diabetes (95.8% ± 10.6%, 85.4% ± 9.2% and 94.1% ± 11.7% of the control, respectively), indicating that TNFSF15 mediates the expression of TJPs." (PMID 27120595, 2016). "Alterations in the regulation of occludin and consequent disruption of tight junctions have been associated with a variety of age-associated diseases such as inflammatory bowel disease, multiple sclerosis, cancer, diabetes and allergic disorders." (PMID 24643011, 2014). "Furthermore, VEGF affects the tight junction protein occludin, inducing occludin phosphorylation and redistribution; resultant occludin reduction is associated with BRB breakdown in diabetes." (PMID 17293777, 2007). "Interestingly, diabetes and advanced age can cause a slight increase in serum occludin levels." (PMID 33269096, 2020). "The impact of diabetes on the tight junction proteins claudin-5, occludin, and ZO-1 was assessed in retinal wholemounts and homogenates by immunofluorescence and Western blot, respectively." (PMID 40898311, 2025). "In agreement, HG and AGE drive BBB disruption in diabetes through increased Cldn5 and occludin expression, highlighting BBB protection as a potential therapeutic strategy to prevent diabetes-associated cognitive decline." (PMID 40940757, 2025). "Our findings suggest that APN induces Occludin expression both through transcriptional regulation and post-translational modifications, thereby exerting protective effects against diabetic vascular endothelial injury (Graphic Abstract)." (PMID 39354565, 2024). "The data unequivocally demonstrates elevated serum levels of Occludin, accompanied by observable fragmentation patterns, within the context of diabetes, as evidenced by Western blot analysis." (PMID 39354565, 2024). "BBB leakage is also accompanied by the down-regulation of claudin-12, occludin, and ZO-1 in obesity with concomitant type II diabetes, or of claudin-5 and occludin in diabetes." (PMID 38891789, 2024). "For a comprehensive analysis of plasma Occludin levels in individuals with diabetes, a series of systematic experiments were conducted." (PMID 39354565, 2024). "The expression of significant proteins of the BBB, such as ZO-1 and occludin, was also evaluated; these results indicated that insulin injections reversed the effects of diabetes and hyperglycemia in the mice and exerted positive effects on the BBB." (PMID 39063010, 2024). "In the diabetes, Occludin serves as a downstream target gene intricately regulated by the adiponectin (APN) signaling pathway." (PMID 39354565, 2024). "On the other hand, weak staining and uneven occludin distribution were observed in mice with diabetes." (PMID 37766457, 2023). "Our findings reveal lower occludin levels in individuals with prediabetes after glucose infusion as well as in patients with diabetes and in diabetic mice urinary bladders." (PMID 36127330, 2022). "The phosphorylation status of occludin is important in disease pathology- in response to diabetes an increase in VEGF mediated phosphorylation of occludin leads to a loss of iBRB integrity and subsequent vision loss." (PMID 34867185, 2021). "In this study, we used a leptin receptor-deficient (db/db) mouse model, to investigate the effects of Azilsartan on diabetes-associated BBB permeability and the expression of tight junction protein occludin." (PMID 34266350, 2021).
diabetes (continued). "The mRNA levels of ZO-1, occludin, and claudin-1 expressed in the intestine decreased in the DM group, indicating that diabetes induction with STZ destroyed the intestinal barrier function." (PMID 34692563, 2021). "RSV significantly attenuated diabetes-induced downregulation of occludin and diabetes-induced upregulation of high-mobility group box-1 (HMGB1), as well as the receptor for advanced glycation end products and BRB breakdown in diabetic retina." (PMID 33525499, 2021). "Decreased VE-cadherin (cadherin-5) has been reported in a human diabetic retina, with normal distribution of tight junction proteins ZO-1 and occludin." (PMID 32414036, 2020). "In this regard, idebenone was previously reported to decrease the permeability of the blood–brain barrier by up-regulating occludin and ZO-1 proteins in a rat model of diabetes." (PMID 31940911, 2020). "Only one report showed diabetes decreased occludin expression at the mRNA and protein level and leads to increase of BSCB permeability." (PMID 28794417, 2017). "In the current work, we observed that diabetes decreased retinal occludin and claudin-5 levels in nine-month-old rats." (PMID 28367226, 2017). "In diabetes, increased BRB permeability is associated with reduced expression of tight junction (claudin-5, ZO-1, and occludin) and adherens (VE-cadherin) proteins." (PMID 25918731, 2015). "We observed that the levels of occludin, a barrier protein, decreased by around 50% to 60% between 3 and 6 months after induction of diabetes, which is consistent with the results of Antonetti and colleagues." (PMID 21139695, 2010). "Diabetes significantly altered this configuration, with less defined occludin-immunoreactivity in TJ complexes, showing a cytoplasmic staining pattern rather than being localised at the plasma membrane." (PMID 17641742, 2007). "Diabetes also had a profound effect on integrity of tightjunctions, as determined by immunolocalization of thejunctional complex component protein occludin in retinal flatmounts." (PMID 17641742, 2007). "Finally, we found that plasma Occludin levels were increased in patients with diabetes compared to the healthy group, and Occludin concentration was negatively correlated with APN level in the setting of diabetes." (PMID 39354565, 2024). "Clinically, elevated plasma concentrations of Occludin were observed in patients with diabetes." (PMID 39354565, 2024). "After adjusting for age, sex, family history of hypertension, coronary heart disease, hyperlipidemia, diabetes, and current smoking, a high level of baseline serum occludin (>0.376 ng/mL) distinguished severe PHE patients from mild PHE (OR, 5.3; 95% CI, 1.9–14.4; p = 0.001)." (PMID 37721332, 2024). "Firstly, we identified elevated plasma Occludin levels in diabetes through Western blot analysis." (PMID 39354565, 2024). "This indicates that reduced Occludin levels may be a significant factor in the vascular dysfunction observed in diabetes." (PMID 39354565, 2024). "Furthermore, this study is the first to demonstrate a significant elevation in plasma Occludin levels in the context of diabetes." (PMID 39354565, 2024). "Notably, in individuals with diabetes, there is a notable reduction in Occludin levels within retinal vascular endothelial cells." (PMID 39354565, 2024). "Expression of occludin in the colon was downregulated by diabetes in both WT and 5-HT4R KO mice." (PMID 37766457, 2023). "Notably, the dense staining pattern of occludin was repaired by the 5-HT4R agonist in mice with diabetes." (PMID 37766457, 2023). "Since the RPE forms part of the blood-retina barrier through tight junctions, we investigated whether mtDNA background and diabetes history affect levels of tight junction proteins, such as ZO-1 and occludin." (PMID 36882486, 2023).